IGLV4-69 (immunoglobulin lambda variable 4-69)
Description:
V region of the variable domain of immunoglobulin light chains that participates in the antigen recognition. Immunoglobulins, also known as antibodies, are membrane-bound or secreted glycoproteins produced by B lymphocytes. In the recognition phase of humoral immunity, the membrane-bound immunoglobulins serve as receptors which, upon binding of a specific antigen, trigger the clonal expansion and differentiation of B lymphocytes into immunoglobulins-secreting plasma cells. Secreted immunoglobulins mediate the effector phase of humoral immunity, which results in the elimination of bound antigens. The antigen binding site is formed by the variable domain of one heavy chain, together with that of its associated light chain. Thus, each immunoglobulin has two antigen binding sites with remarkable affinity for a particular antigen. The variable domains are assembled by a process called V-(D)-J rearrangement and can then be subjected to somatic hypermutations which, after exposure to antigen and selection, allow affinity maturation for a particular antigen.
Synonyms: IGLV469; V5-6
Gene: Immunoglobulin variable (V) gene on chromosome 22 (22,030,934 to 22,031,472, forward strand). Ensembl gene ENSG00000211637.
Subcellular location: Secreted; Cell membrane
Gene Ontology:
Biological process: immune response
Cellular component: extracellular region; immunoglobulin complex; plasma membrane
Homologues: Orthologues: chimpanzee IGLV4-69 (82% identical), macaque IGLV4-69 (76% identical). Paralogues in human: IGLV4-60 (81% identical), IGLV9-49 (64% identical), IGLV4-3 (61% identical), IGLV5-37 (60% identical), IGLV5-52 (58% identical), IGLV5-45 (56% identical), IGLV11-55 (51% identical), IGLV5-48 (50% identical), IGLV1-40 (48% identical), IGLV1-44 (48% identical), IGLV1-47 (47% identical), IGLV2-18 (47% identical), and 81 more.